CRP (C-reactive protein)
Diseases named in the same sentence as CRP in open-access papers (continued):
Sharing a sentence is not in itself a finding about the gene and the disease.
diabetes (continued). "Finally, once supplementary adjustments for C-reactive protein (CRP) and insulin resistance were performed, participants with diabetes continued to show significantly decreased FEV1 and FVC values, reinforcing the potential role of other mechanisms underlying this negative association." (PMID 33148273, 2020). "Another study reported that hs‐CRP levels were higher in diabetes patients with ED compared with those without ED, but the present study did not target the specific population of men aged >55 years, and included younger men without measurement of the sex steroids levels." (PMID 31148390, 2020). "Additionally, higher CRP concentration is significantly associated with higher odds of nephropathy and PAD in non-diabetes and higher odds of PAD in diabetes." (PMID 32665312, 2020). "In addition, we assessed associations between CRP and microvascular (nephropathy) and macrovascular dysfunction (PAD) in Ghanaians with and without diabetes." (PMID 32665312, 2020). "In contrast, CRP was not a significant predictor of cancer death (HR: 0.96; 95% CI 0.54–1.59), after adjustment for traditional risk factors (age, sex, race, alcohol intake, HEI, smoking, BMI, dyslipidemia, HTN, and diabetes) and the apoB/apoA-I ratio." (PMID 31936330, 2020). "Based on the results of univariate analysis, we analysed miR-33a along with age, BMI, waist circumference, diabetes, glycaemia, HbA1c, C-peptide, HOMA-IR, triglycerides, total cholesterol plasma concentration, glomerular filtration rate (MDRD-GFR) and C-reactive protein (CRP)." (PMID 31703079, 2019). "By comparison, patients in the END group had a higher prevalence of diabetes mellitus (DM; 41% vs. 19%, p = 0.001), higher median baseline NIHSS scores (5 vs. 2, p = 0.001), and higher hs‐CRP levels (5.6 vs. 1.7, p = 0.016)." (PMID 31025553, 2019). "Those who experienced HF during follow-up were generally older, had higher BMI and waist circumference, were more likely to have diabetes, had lower FEV1 and eGFR, had higher heart rate, were more likely to be on blood pressure–lowering medication and to have atrial fibrillation and higher CRP." (PMID 30103019, 2019). "Age, duration of AS, HLA-B27 positivity, the presence of hyperuricemia, hypertension, diabetes or kidney stones, ESR, CRP, serum albumin, triglyceride and total cholesterol, which might be associated with CKD development, were introduced into the multiple logistic regression model." (PMID 31818273, 2019). "However, the CRP values of patients with end stage renal disease, notably of patients with diabetes mellitus, are in absence of an infection higher than CRP values of people without end stage renal disease." (PMID 31151433, 2019). "eGFR = estimated glomerular filtration rate; ACR = albumin creatinine ratio, DM = diabetes mellitus, IHD = ischaemic heart disease, PVD = perivascular disease, CRP = c-reactive protein, uLG1M = urinary LG1M/Creatinine." (PMID 30273365, 2018). "Diabetes status can be measured directly from biomarkers, such as fasting blood glucose (FBG), but also because insulin resistance (IR) and inflammation are important hallmarks of T2DM, biomarkers of inflammation, such as C-reactive protein (CRP), are also relevant." (PMID 30096929, 2018). "Interestingly, although C-reactive protein (CRP) and plasminogen activator inhibitor-1 (PAI-1) have both been described as being associated with insulin resistance and diabetes, a negative association of these with birthweight has been found." (PMID 29370080, 2018). "Furthermore, the combined model II (RBP4/HOMA-IR/diabetes duration/Hs-CRP/HbA1c) did not improved the ability of model I to diagnose VTDR (AUC of the combined model 0.94; 95% CI: 0.86–0.96; P>0.05)." (PMID 30135138, 2018).
diabetes (continued). "Treatment with either rosiglitazone (4–8 mg daily for 8 to 26 weeks) or pioglitazone (45 mg daily for 3 months) significantly reduced C-reactive protein (CRP) levels in patients with diabetes as well as in non-diabetic patients with coronary artery disease and rheumatoid arthritis." (PMID 29414995, 2018). "Similar to previous reports in other disease cohorts, we found that high CRP levels were associated with both AF and COPD, but we did not identify an association between CRP and other individual comorbidities, such as diabetes mellitus and ischemic heart disease." (PMID 30114262, 2018). "Among the top modulated adipokines were inflammatory mediators (C-reactive protein, endocan, EN-RAGE), extracellular matrix regulating factors (Serpin A8, TIMP-1, TIMP-3), and resistin, an adipokine proposed to be an important link between obesity and diabetes." (PMID 30524378, 2018). "TGs were also inversely associated with infectious mortality in the univariate model (HR: 0.75; 95% CI: 0.69–0.81), as well as in the models adjusted for demographics, diabetes, serum creatinine, and CRP (models 1–3 and 5) but not following adjustment for serum albumin (models 4 and 6)." (PMID 29895699, 2018). "However, a chronic increase in inflammatory markers, such as interleukin (IL)-6, IL-1, tumor necrosis factor α (TNF-α), and C-reactive protein (CRP), plays a key role in various chronic conditions (e.g., type 2 diabetes mellitus [T2DM], cardiovascular diseases [CVDs], and cancer)." (PMID 29495330, 2018). "When we divided our cohort into patients with high and low total plaque volumes, some (age, sex, hypertension, smoking, hs-CRP, HDL cholesterol, and triglycerides) but not all (BMI, hyperlipidaemia, diabetes mellitus) risk factors were significantly associated with plaque formation." (PMID 30602707, 2018). "Model 1: adjusted for age, gender, race/skin color; Model 2: model 1 plus hypertension, diabetes mellitus, dyslipidemia, smoking, BMI, HDL-cholesterol, triglycerides, glomerular filtration rate by CKD-Epi (Chronic Kidney Disease Epidemiology Collaboration), and C-reactive protein." (PMID 29561960, 2018). "For example, there is evidence that high serum C-reactive protein (CRP) is related to overweight or obese status and also involved in the development of several chronic diseases such as obesity, cardiovascular diseases, type 2 diabetes mellitus, and colorectal and other cancers." (PMID 28115972, 2017). "In these studies, CRP was a significant predictor of CVD only among participants without diabetes." (PMID 28435446, 2017). "Low AGE diets were found to decrease insulin resistance in the whole group, decrease total and low density lipoprotein (LDL)-cholesterol in those without diabetes, and decrease fasting insulin and C-reactive protein (CRP) in people with type 2 diabetes (n = 112)." (PMID 29232895, 2017). "A significant impact of diabetes mellitus on the CRP and leukocytes could not be observed, but a tendency was found." (PMID 28809368, 2017). "However, the current analysis along with prior studies have shown that the association between FGF-21 and diabetes was independent of lipids (TG, HDL-C), inflammatory marker (hs-CRP) and liver enzymes (GGT, ALT)." (PMID 29021814, 2017). "The concentrations of E-selectin and CRP in the blood serum were higher, and the concentrations of IL-6 and fibrinogen were lower in patients suffering from controlled type 2 diabetes than in patients without diabetes." (PMID 27834825, 2016). "However, traditional risk factors including age, body mass index (BMI), hypertension, diabetes, SBP, homeostasis model assessment-estimated insulin resistance (HOMA-IR), fasting glucose concentration and hs-CRP level were significantly increased with the increment of UACR." (PMID 28000719, 2016). "Alternatively, CRP did not improve prediction probability of diabetes (data not reported)." (PMID 27013319, 2016).
diabetes (continued). "It is suggested that in the pathogenesis of PAD in patients suffering from diabetes, a significant role is played by pro-inflammatory cytokines and acute-phase proteins; the mentioned elements include interleukin-6 (IL-6), tumor necrosis factor (TNF)-alpha, C-reactive protein (CRP), and fibrinogen." (PMID 27834825, 2016). "In the group of patients without diabetes, such a role may be assigned to CRP and E-selectin, which are indicators of endothelial function." (PMID 27834825, 2016). "Some studies explicitly indicate a relationship between CRP and complications of diabetes; nonetheless, evidence is lacking for a direct mechanism, and CRP may very well merely be a marker of the ongoing inflammation [80•, 87–89]." (PMID 25648962, 2015). "In reports from which we could source data, we found negative associations between mean HDL-C levels and diabetes prevalence, WHR and CRP levels, all well-recognised CVD risk factors in Indigenous communities." (PMID 24888391, 2014). "Also, hs-CRP and PAI-1 have shown to be predictors of incipient diabetes." (PMID 24772446, 2014). "Consequently, negative coefficients of CRP, diabetes, and fatty liver on TRECs were observed in both CD4 and CD8 T cells." (PMID 24651652, 2014). "The mean CRP level in the overall population was 4.2 mg/L, and this was similar to levels seen in the subgroup of patients without diabetes mellitus who were not receiving statin therapy, and in the subgroup of those at intermediate risk and not receiving statin therapy." (PMID 24564178, 2014). "Thus, almost a quarter (23.3%) of the EURIKA study patients without diabetes mellitus and not already taking a statin were found to be at intermediate risk by SCORE and had CRP levels ≥2 mg/L (17% had CRP levels ≥3 mg/L)." (PMID 24564178, 2014). "The subgroup analysis was performed to examine the effect of the various factors on predicting microalbuminuria; the factors studied were age, gender, the presence or absence of diabetes mellitus, blood pressure, CRP, urine creatinine level, eGFR, and the use of drugs (ACEi/ARB/AldB/DRI and statin)." (PMID 24614247, 2014). "The following hypotheses were tested: Participants with low n-3 intake, regardless of ethnicity and diabetes status, will be more likely to have: 1) high CRP, and 2) high HCY." (PMID 31667003, 2013). "Along with coronary arterial damage and inflammatory processes, high-sensitivity C-reactive protein is considered as an essential atherosclerosis marker in patients with cardiovascular disease, but not as an insulin resistance marker in type 2 diabetes mellitus patients." (PMID 24282409, 2013). "Hypertension, obesity, hyperlipidemia, and diabetes, the main manifestations of metabolic syndrome, do not always present simultaneously, while in obese patients, the presence of at least three of these manifestations can lead to CRP elevation." (PMID 23978069, 2013). "Diabetes mellitus contributes to CAS development in men with low hs-CRP levels, but not in women." (PMID 24204905, 2013). "Studies have reported that CRP levels are higher in subjects with type 1 and type 2 diabetes compared with those without diabetes, while another study not find any correlation between CRP levels and titer of autoantibodies in long-term type 1 individuals with type 1 diabetes." (PMID 24499591, 2013). "Moreover, these associations are independent of lifestyle factors, duration of diabetes, family history of diabetes, and, remarkably, CRP, HbA1c, HOMA-IR and BMI." (PMID 23342952, 2013). "Whether or not these CRP reductions can translate into decreased rates of clinical cardiovascular disease or diabetes development remains to be determined in future clinical trials as no such trial has been conducted to date." (PMID 24155956, 2013). "Diabetes status and consumption of n-3 did not significantly predict odds of high CRP or high HCY." (PMID 31667003, 2013).
diabetes (continued). "However these results are inconclusive and only a few articles in the literature analyze the relationship between CRP and periodontal disease in patients with diabetes and none of them are done with type 1 diabetic individuals." (PMID 22322513, 2012). "Those with diabetes were more likely to be older, obese, had higher prevalence of hypertension, depression and higher levels of CRP, less likely to be non-Hispanic whites, above high school educated, current smokers, current drinkers, physically active, and had lower levels of total cholesterol." (PMID 22518133, 2012). "In neither of the cohorts did diabetes mellitus, arterial hypertension, compensated heart insufficiency, nor a history of prior lumbar nucleotomy in another segment have any influence on CRP or leukocyte kinetics postoperatively compared to patients without these comorbidities." (PMID 21657968, 2011). "Moreover, these associations are independent of lifestyle factors, eGFR, duration of diabetes, family history of diabetes and remarkably, CRP, HbA1C, HOMA-IR and BMI." (PMID 21816063, 2011). "Commonly used clinical measurements such as BMI and other inflammatory biomarkers did not differentiate types of diabetes in AA which are different from studies involving Caucasian and other minority populations that show BMI and CRP are reliable predictors of type 2 diabetes." (PMID 22164267, 2011). "Changes in CRP were not significant for individuals with diabetes." (PMID 20123638, 2010). "In either case, the extremely high CRP concentrations seen in the DRUID women could presage extremely high rates of diabetes and CHD, although no prospective data is available to confirm this." (PMID 21078191, 2010). "CRP levels were lower in S319 allele carriers of the HNF1A gene compared to non-carriers among individuals without diabetes, but this difference was not present among those with diabetes, who uniformly had elevated CRP levels." (PMID 20716378, 2010). "In addition, the difference in CRP levels between the S319 carrier statuses was not present in those with diabetes, who are likely under chronic inflammatory stress." (PMID 20716378, 2010). "Pearson’s correlations showed that ln hs-CRP was significantly correlated with WC (r = 0.470, p = 0.001 and r = 0.406, p = 0.001) and BMI (r = 0.387, p = 0.001 and r = 0.395, p = 0.001) among females with and without diabetes." (PMID 20617007, 2010). "However, the elevated CRP levels in underweight diabetics suggest that inflammation may also play a role in non-obese forms of diabetes." (PMID 41523554, 2025). "Exploring its impact across different patient profiles, such as oncologic versus non-oncologic individuals, various types of diabetes, insulin use, or baseline CRP, could provide valuable insights into how these treatments influence muscle decline in distinct pathophysiological contexts." (PMID 41156461, 2025). "Notably, the pro-inflammatory markers C-reactive protein (CRP), interleukin-1β (IL-1β), interleukin-6 (IL-6), NF-kB, and tumor necrosis factor-alpha (TNF-α) contribute to the chronic inflammatory state of T2DM and are significantly elevated in patients with diabetes." (PMID 39062550, 2024). "The relationship between LRINEC scores and risk factors, such as gender, comorbidities (diabetes mellitus [DM] and peripheral vascular disease [PVD]), recent trauma, C-reactive protein (CRP) levels, white blood cell count (WBC) counts, and creatinine levels, was assessed." (PMID 39677092, 2024). "Interestingly, ZW inhibited diabetes-induced anxiety and depression by minimizing the neuroinflammatory response by decreasing NfκB, IL-1β, and IL6 mRNA levels and the number of TNF-α- and GFAP-immunostained neurons and serum level of TNF-α and CRP because of its antioxidant power." (PMID 38105928, 2023).
diabetes (continued). "However, it is important to note that this study only adjusted for age, smoking, gender, hypertension, body mass index (BMI), drinking, diabetes, and high-sensitivity C-reactive protein (hs-CRP) when analyzing the relationship between the non-HDL-c/HDL-c ratio and stroke." (PMID 38288470, 2023). "Data showed that GSDMD level was associated with CRP (Pearson correlation: 0.289, P = 0.001) and hypertension (Pearson correlation: 0.185, P = 0.024), but there was no statistical correlation between GSDMD level and diabetes (Pearson correlation: −0.102, P = 0.215)." (PMID 36544106, 2022). "Diabetes (DM) is denoted by the letters MLR (monocyte-to-lymphocyte ratio), CRP (c-reactive protein), PCT (procalcitonin), NLR (neutrophil-to-lymphocyte ratio), PLR (platelet-to-lymphocyte ratio), NIHSS (National Institutes of Health Stroke Scale score), and GCS (Glasgow Coma Score)." (PMID 36072574, 2022). "In a study of SRP in periodontal patients with diabetes, it was reported that there was no change in HbA1c and serum biomarkers (hs-CRP, TNF-α, IL-6) during the 6-month follow-up period, regardless of whether SRP was performed and the severity of periodontal disease." (PMID 36140045, 2022). "Moreover, hyperglycemia in diabetes could be controlled by GNPs via improving blood glucose levels, insulin resistance, and liver enzymes, reducing proinflammatory cytokines (include TNF-α, IL-6, and CRP), and enhancing the antioxidant defense enzymes." (PMID 34572503, 2021). "However, the possibility of obesity‐related comorbidities such as hypertension, diabetes, and probably high infection contributing to elevated CRP levels, could not be excluded." (PMID 33680494, 2021). "IQR, interquartile range; CAD, coronary artery disease; COPD, chronic obstructive pulmonary disease; OSA, obstructive sleep apnea; HTN, hypertension; DM, diabetes mellitus; CRP, C-reactive protein; LDH, lactate hydrogenase; FEU, fibrinogen equivalent units; TCZ, tocilizumab." (PMID 33489621, 2020). "Finally, we found that diabetes duration did not affect pulmonary function, and the deleterious effect of diabetes on pulmonary function was mediated by hyperglycemia, insulin resistance, low-grade chronic inflammation (CRP), and obesity." (PMID 33148273, 2020). "However, it may not be optimal to evaluate baseline hs-CRP and incident diabetes because baseline hs-CRP could not reflect longitudinal changes in inflammation status." (PMID 32612667, 2020). "However, the baseline level of ApoA-I glycation in patients with diabetes was higher than in those without diabetes, which is one of the reasons for the inverse relationship between the relative intensity of ApoA-I glycation and CRP, BNP, cTNI, and LVEF." (PMID 30259778, 2018). "However, when we separately compare the evolution of hs-CRP and HbA1c in the well-controlled diabetes patients group and in the non-controlled diabetes patients group, correlation between HbA1c and hs-CRP become non-significant probably because of our sample size." (PMID 28886725, 2017). "Comparing CVD risk factors by diabetes status for each gender, girls with T1D had higher A1c (p < 0.0001), BMI Z-score (p = 0.005), total cholesterol (p = 0.002), LDL-c (p = 0.001), SBP (p = 0.0006), DBP (p < 0.0001), and hs-CRP (p = 0.002) compared to non-DM girls." (PMID 27099615, 2016). "Furthermore, inflammatory markers such as C-reactive protein and IL-6 are predictive of diabetes even in nonobese subjects, suggesting that inflammation, not obesity per se, may be the major culprit in disease pathogenesis." (PMID 26146464, 2015). "Of patients without diabetes mellitus who were not receiving statin treatment, more than one-third (range: 34.0 to 41.3%) of patients in each risk category, whether classified according to either SCORE or FRS, had CRP levels ≥3 mg/L." (PMID 24564178, 2014).